STC1 (stanniocalcin 1)
Diseases named in the same sentence as STC1 in open-access papers (continued):
Sharing a sentence is not in itself a finding about the gene and the disease.
metastatic disease (2 papers, 2015 to 2025). "In the current study, we were able to determine that plasma STC1 levels were elevated in the setting of chemotherapy-resistant patients compared with samples taken at diagnosis of metastatic disease prior to any treatment." (PMID 39807836, 2025). "Our analysis of STC1 mRNA expression in ccRCC tumors of different stages revealed that STC1 expression was up-regulated in T1 stage metastatic tumors when compared with localized tumors." (PMID 25740019, 2015). "Elevated expression of STC1 protein was also observed in tumor tissues when compared with non-tumor tissues, again with the highest expression observed in metastatic tumors." (PMID 25740019, 2015). "A comparison of STC1 mRNA expression between localized and metastatic tumors, revealed that only T1 stage tumors exhibited a statistically significant difference in STC1 expression when compared with other tumor stages (P = 0.021)." (PMID 25740019, 2015). "STC1 expression was elevated in T1 stage metastatic tumors when compared with localized tumors, and was positively correlated with average tumor diameter." (PMID 25740019, 2015). "Indeed, although ANG2 levels are comparable in plasma of patients at diagnosis of their metastatic disease and after resistance to chemotherapy, STC1 levels are clearly higher following progression on several lines of chemotherapy." (PMID 39807836, 2025). "Also, STC1 mRNA expression in T2 and T3 metastatic tumors was much higher than that in localized tumors, which barely achieved statistical significance." (PMID 25740019, 2015).
neuroblastoma (2 papers, 2011 to 2020). Neuroblastoma (NB) is the most common solid, extracranial childhood tumor. "For instance, activation of Akt could increase NF-κB activity via phosphorylation of IKK, while the negative effect of NF-κB on STC1 expression was reported in the mouse neuroblastoma cell model." (PMID 22069492, 2011).
papillary thyroid cancer (2 papers, 2024 to 2025). "SNAI1 and STC1 in papillary thyroid cancer need to be further investigated to determine whether they can be used as predictors to guide the prognosis as well as the treatment of papillary thyroid cancer." (PMID 40295497, 2025).
renal carcinoma (2 papers, 2015 to 2023). A carcinoma arising from the epithelium of the renal parenchyma or the renal pelvis. "Our data provide an insight into the possible role of STC1 in renal cancer cell survival under hypoxic conditions." (PMID 25740019, 2015). "Immunohistochemical staining demonstrated that the STC1 protein was predominantly localized in the cytoplasm of both renal cancer tissues and normal renal tissues." (PMID 25740019, 2015).
viral infection (2 papers, 2018 to 2023). "Quantitative real-time PCR and western blot analysis showed a remarkable increase in the levels of STC1 transcript and protein in S1 cells, illustrating the high efficacy of the viral infection." (PMID 29467934, 2018). "STC1 knock-down led to a modest effect on the production of encapsidated viral genomes (average relative decrease of 29%, p = 0.0093) at 5 days post-infection in the conditions with the virus infections at a multiplicity of infection (MOI) at 0.5." (PMID 37740179, 2023). "Small interfering RNAs (siRNAs) were used to assess the impact of STC1 and FLT4 expression on viral infection and angiogenesis." (PMID 37740179, 2023).
acute respiratory distress syndrome (1 paper, 2024). Progressive and life-threatening pulmonary distress in the absence of an underlying pulmonary condition, usually following major trauma or surgery. "STC-1 secreted by human umbilical MSCs can promote the secretion of IL-10 in alveolar macrophages, thus alleviating the inflammatory storm caused by acute respiratory distress syndrome." (PMID 38693589, 2024).
altitude sickness (1 paper, 2024). Multiple symptoms associated with reduced oxygen at high altitude. "By using gene expression data analysis and functional experiments, we identified STC1 as a key gene affecting the development of altitude sickness." (PMID 39201771, 2024).
colon adenoma (1 paper, 2020). An adenoma that arises from the colon. "Co-treatment of human colon adenoma cells with trichostatin A and PN significantly inhibited the trichostatin A-induced cellular levels of acetyl NF-κB/p65 and decreased NF-κB/p65 binding to the promoter of putative tumor suppressor gene, stanniocalcin-1 (STC1)." (PMID 32823992, 2020).
colorectal tumor (1 paper, 2014). "Pena and colleagues identified stanniocalcin 1 (STC1) as a protein secreted by CAFs stimulating the metastatic behavior of colorectal tumor cells." (PMID 24978438, 2014).
coronary artery diseases (1 paper, 2021). "Among hypoxia-responsive genes identified in our in vitro hypoxic system, we also found potential cardiac biomarkers (BIRC5, ENG, HMOX1, VEGF, STC1, STC2, and SERPINE1) which they may have potential clinical value in the diagnosis and prognosis of coronary artery diseases." (PMID 34685725, 2021).
diabetic nephropathy (1 paper, 2025). "Data from diabetic nephropathy patients, characterized by microvascular dysfunction, have demonstrated that patients with high levels of STC1 have a better prognosis than patients with low STC1 levels." (PMID 41249792, 2025).
dilated cardiomyopathy (1 paper, 2012). Cardiomyopathy which is characterized by dilation and contractile dysfunction of the left and right ventricles. "Since STC1 is upregulated in the heart in patients suffering from dilated cardiomyopathy, we reasoned that STC1 may play a role in suppressing Ang II-mediated ROS." (PMID 22693564, 2012).
endometrial cancer (1 paper, 2021). Primary or metastatic malignant neoplasm involving the endometrium (mucous membrane that lines the endometrial cavity). "For EC, this observation may be caused by the fact that high-grade (grade 3) endometrial cancers are more disorganized, whereas in benign circumstances, endometrial STC-1 is highly expressed in the normal epithelium." (PMID 34650342, 2021). "The role of STC-1 in endometrial cancer (EC) is yet to be elucidated." (PMID 34650342, 2021).
endometrioid tumor (1 paper, 2021). A benign, borderline, or malignant epithelial tumor of the female reproductive system characterized by the presence of glands and/or cysts lined by neoplastic cells that resemble endometrial cells. "Decreased STC-1 expression was associated with factors relating to a worse prognosis, such as grade 3 endometrioid tumors (p = 0.030), deep myometrial invasion (p = 0.003), lymphovascular space invasion (p = 0.050), and large tumor size (p = 0.001)." (PMID 34650342, 2021).
endothelial dysfunction (1 paper, 2025). In vascular diseases, endothelial dysfunction is a systemic pathological state of the endothelium (the inner lining of blood vessels) and can be broadly defined as an imbalance between vasodilating and vasoconstricting substances produced by (or acting on) the endothelium. "In addition, STC1 may be the principal paracrine factor released by MSCs, which regulates mitochondrial dynamics remodeling through inhibiting ERK1/2-Drp1 axis and, consequently, preventing mtROS overproduction, inflammatory, apoptosis and resultant endothelial dysfunction." (PMID 41249792, 2025).
esophageal tumors (1 paper, 2012).
female infertility (1 paper, 2024). Diminished or absent ability of a female to achieve conception. "STC1 and STC2 contribute to the pathophysiology of several diseases, including female infertility- and pregnancy-associated conditions, and even tumorigenesis of reproductive organs." (PMID 39186548, 2024).
gestational diabetes mellitus (1 paper, 2024). "Stanniocalcin-1 (STC-1) is a pleiotropic hormone that is important for maintaining female reproductive health and shows a sharp placental expression peak in mid-gestation, and its increased mRNA level has been detected in pregnancy complications such as PE or gestational diabetes mellitus." (PMID 38455065, 2024).
glomerular basement membrane disease (1 paper, 2015). "Anti-inflammatory action of STC1 on endothelial cells and macrophages was reported and was demonstrated in a model of anti-glomerular basement membrane disease in STC1-transgenic mice." (PMID 26469082, 2015).
gout (1 paper, 2022). A condition characterized by painful swelling of the joints, which is caused by deposition of urate crystals. "An STC1 SNP (rs17786744) might cause the crystalline precipitation of sodium urate to trigger the inflammatory process, further exacerbating cartilage damage and promoting knee osteoarthritis, which could be associated with the inflammatory response in gouty arthritis." (PMID 35813212, 2022).
head and neck cancer (1 paper, 2022). A primary or metastatic malignant neoplasm affecting the head and neck. "Our results indicate that the roles of STC1 in ATP synthesis and cancer metabolism are consistent with recent reports for other cancer cell types, as metastasis rates in head and neck cancer cells were decreased when iATP levels were reduced." (PMID 36499099, 2022).
hypocalcaemia (1 paper, 2017). "Stanniocalcin-1 (STC1) is a secreted glycoprotein hormone, which was first identified as a hypocalcaemia hormone functioning importantly for the maintenance of calcium homeostasis in teleost fish." (PMID 28545028, 2017).
idiopathic dilated cardiomyopathy (1 paper, 2012). Decreased function of the heart associated with cardiac enlargement and congestive heart failure, of unknown cause. "Previous data from our laboratory demonstrated upregulation of the mammalian homologue of fish STC1 in the hearts of patients suffering from idiopathic dilated cardiomyopathy (DCM)." (PMID 22693564, 2012). "We have previously shown increased cardiac stanniocalcin-1 (STC1) in patients with idiopathic dilated cardiomyopathy." (PMID 22693564, 2012).
inflammatory bowel disease (1 paper, 2021). A spectrum of small and large bowel inflammatory diseases of unknown etiology. "Previous research on patients with inflammatory bowel disease (IBD) has identified several genes (IL13RA2, TNFRSF11B, STC1, IL-6, and IL-11) that constitute potential biomarkers that can identify patients with limited response to IFX, which is consistent with our study." (PMID 34650991, 2021).
intestinal cancer (1 paper, 2014). "Additionally, endogenously expressed GUCY2C internalized to lysosomes in STC1 murine intestinal cancer cells." (PMID 25294806, 2014).
ischemia (1 paper, 2025). A hypoperfusion of the BLOOD through an organ or tissue caused by a PATHOLOGIC CONSTRICTION or obstruction of its BLOOD VESSELS, or an absence of BLOOD CIRCULATION. "Besides, we observed that the slightly increased serum Stc1 level during ischemia fall back after reperfusion in mouse MI/R injury models." (PMID 39676707, 2025).
liver fibrosis (1 paper, 2022). "Next, siSTC1-SHED-Heps were transplanted into CCl4-treated mice (siSTC1-SHED-HepTx mice) and compared to siCONT-SHED-Hep transplanted CCl4-treated mice (siCONT-SHED-HepTx mice) to examine the benefit of STC1 to liver fibrosis." (PMID 36113772, 2022).
Lowe syndrome (1 paper, 2021). "Stc1: Stanniocalcin1; TGFb: TGF-b; AgII: Angiotensin II; LRP2: Megalin; OCRL1: Gene mutated in Lowe Syndrome; PIKfyve: FYVE finger-containing phosphoinositide kinase (functions along OCRL1); TGN: Trans Golgi Network; ER: Endoplasmic Reticulum." (PMID 35098216, 2021).
lung adenoma (1 paper, 2020). A benign, well circumscribed epithelial neoplasm that arises from the bronchus or the lung parenchyma. "Our secretome analysis using the V600EBRAF-driven mouse lung adenoma model identified stanniocalcin-1 (STC1) as a candidate mediator of tumor-TME interactions." (PMID 32579928, 2020). "To investigate the role of STC1 in lung adenoma/adenocarcinoma progression, we have analyzed two genetically engineered mouse (GEM) models: one driven by G12DKRAS leading to adenocarcinoma development, and the other by V600EBRAF generating pre-malignant adenomas." (PMID 32579928, 2020).
lung injury (1 paper, 2015). "Our data identify new and previously unrecognized cytokines/chemokines that appear to play a role in the pathogenesis of bleomycin-induced acute lung injury; transgenic overexpression of STC1 blunts the expression of these cytokines/chemokines." (PMID 26640170, 2015).
mastitis (1 paper, 2018). Inflammation of breast tissue during lactation or postpartum due to an obstructed duct or infection. "On the other hand, our qRT-PCR analyses supported the downregulation of PLAUR and IFNGR1 and the upregulation of STC1 and IL19 in the breast milk SC from women with mastitis after treatment with the probiotic." (PMID 30271395, 2018).
nephritis (1 paper, 2015). Inflammation of renal tissue. "To determine the impact of kidney-specific knockdown of STC1 on the phenotype nephrotoxic nephritis, we utilized STC1 shRNA Tg and scrambled shRNA Tg mice, which we recently described in details." (PMID 26393521, 2015). "We have previously shown rSTC1 stabilizes endothelial barrier function, and diminishes trans-endothelial migration of leukocytes; while transgenic overexpression of STC1 in mice diminishes kidney inflammation in the context of nephrotoxic nephritis." (PMID 26393521, 2015). "While STC1 Tg mice are protected from nephrotoxic nephritis, it was unclear whether the protection is mediated through local effects of STC1 in the kidney, or extra-renal effects due to high circulating levels of rSTC1." (PMID 26393521, 2015).
Osteochondrosis (1 paper, 2018). Abnormal growth ossification centers in children. "Furthermore, the involvement of STC1 in bone formation is supported by its location in a QTL for osteochondrosis-related traits in different pig populations." (PMID 29931419, 2018).
papillary adenoma (1 paper, 2020). An adenoma characterized by the presence of papillary epithelial patterns. "Histological analysis showed that Stc1+/+ SPK tumors retained characteristics of papillary adenomas with mild to moderate dysplasia, whereas Stc1−/− SPK tumors occasionally showed malignant progression to adenocarcinoma." (PMID 32579928, 2020).
periodontal disease (1 paper, 2023). "Furthermore, CXCL5, ADM, FGF9, AIMP1, STC1, and CDKN2A might have a significant impact on the development of HNSC caused by periodontal disease." (PMID 37675228, 2023).
pneumonitis (1 paper, 2015). An inflammatory process affecting the lung parenchyma. "The data suggest that transgenic overexpression of STC1 protects from acute bleomycin-induced lung injury and pneumonitis." (PMID 26640170, 2015). "In conclusion, STC1 blunts bleomycin-induced rise in thrombin protein and activity, diminishes thrombin-induced signaling through PAR1 to ERK, and inhibits bleomycin-induced pneumonitis." (PMID 26640170, 2015). "Stanniocalcin-1 (STC1) activates anti-oxidant pathways, inhibits inflammation and provides cytoprotection; hence, we hypothesized that STC1 will inhibit thrombin/PAR1 signaling and protect from bleomycin-induced pneumonitis." (PMID 26640170, 2015).
prostate tumour (1 paper, 2008). "In addition, there is compelling evidence for the role of several 8p genes in carcinogenesis, including a number studied here, such as the prostate tumour suppressor NKX3.1, TRAILR DR5, DBC2 and STC1." (PMID 18590575, 2008).
rectal cancer (1 paper, 2023). A primary or metastatic malignant neoplasm that affects the rectum. "High STC1 expression was associated with poor PFS in both colon and rectal cancer patients." (PMID 36816947, 2023).
rheumatoid arthritis (1 paper, 2018). A chronic, systemic autoimmune disorder characterized by inflammation in the synovial membranes and articular surfaces. "IPA of annotated transcripts showed similar activation of osteogenic-associated pathways such as roles of osteoblasts, osteoclasts, and chondrocytes in rheumatoid arthritis as well as the expression of typical osteogenic genes such as dlx5, tsc22d3, alpl, klf4, ext1, and stc1 in both datasets." (PMID 30376879, 2018).
seminoma (1 paper, 2023). A radiosensitive malignant germ cell tumor found in the testis (especially undescended), and extragonadal sites (anterior mediastinum and pineal gland). "Results from IHC analysis of 24 seminoma tissues and eight normal tissues revealed a substantial increase in STC1 expression levels in TGCT samples." (PMID 37543714, 2023).
squamous cell carcinoma (1 paper, 2021). A carcinoma arising from squamous epithelial cells. "And also, the expression of STC‐1 was observed in tissues of squamous cell carcinoma and adenocarcinoma, both of which are grouped as non‐small cell lung carcinoma (NSCLC)." (PMID 33826244, 2021).
triple-negative breast carcinoma (1 paper, 2021). An invasive breast carcinoma which is negative for expression of estrogen receptor (ER), progesterone receptor (PR), and human epidermal growth factor receptor 2 (HER2). "In triple negative breast cancer, overexpression of STC-1 could activate the JNK/c-Jun signaling pathway to increase the invasiveness of triple-negative breast cancer cells." (PMID 34663825, 2021).
Wilson disease (1 paper, 2022). A very rare inherited multisystemic disease presenting non-specific neurological, hepatic, psychiatric or osseo-muscular manifestations due to excessive copper deposition in the body. "A previous study demonstrates that SHED-Hep-secreting STC1 suppressed ROS-mediated hepatocyte necrosis in Wilson’s disease model rats." (PMID 36113772, 2022).